GDF15 (growth differentiation factor 15)
Diseases named in the same sentence as GDF15 in open-access papers (continued):
Sharing a sentence is not in itself a finding about the gene and the disease.
atrial fibrillation (continued). "GDF-15 might become part of a biomarker-based bleeding risk score in LVAD patients, similar to the ABC-bleeding score in patients with atrial fibrillation." (PMID 35455481, 2022). "Like common atrial fibrillation (AF) patients, AF patients without traditional risk factors also had high plasma GDF‐15 level." (PMID 35334497, 2022). "In another human study, the relationship between GDF15 levels and atrial fibrosis in patients with atrial fibrillation (AF) and rheumatic heart disease (RHD) was examined." (PMID 40565178, 2025). "To date, GDF-15 has been most extensively studied in cardiovascular diseases, particularly in patients with atrial fibrillation (AF)." (PMID 39967200, 2025). "Analysis of the COMBINE-AF cohort showed that NT-pro BNP, hs TnT, and GDF-15 were significantly associated with a high risk HF events among patients with atrial fibrillation (AF)." (PMID 39407996, 2024). "Indeed, median circulating GDF-15 in our cohort (∼2600 ng/L) was higher compared to patients with chronic coronary artery disease or atrial fibrillation (∼1000–2000 ng/L) or healthy controls (<1000 ng/L) but similar to patients with chronic heart failure (median ∼2000–3000 ng/L)." (PMID 37008733, 2023). "Growth differentiation factor 15 (GDF-15) is a biomarker independently associated with bleeding and death in anticoagulated patients with atrial fibrillation (AF)." (PMID 33741689, 2021). "Moreover, GDF-15 in serum was higher in patients with atrial fibrillation, and it could be used as a prognostic indicator for bleeding and death." (PMID 32904560, 2020). "Significance: GDF-15 and NT-pro-BNP in the pericardial fluid are biomarkers of atrial fibrillation in aortic stenosis and correlate with atrial matrix remodeling." (PMID 34441356, 2021). "An observational study included 894 patients with atrial fibrillation with or without left atrial thrombus revealed that GDF15 serum level was higher in patients with atrial thrombus compared to patients with atrial fibrillation without atrial thrombus." (PMID 36140453, 2022). "An observational study including 894 patients with atrial fibrillation with or without left atrial thrombus revealed that GDF15 serum level was higher in patients with atrial thrombus compared to patients with atrial fibrillation without atrial thrombus." (PMID 36444166, 2022). "In patients with no history of atrial fibrillation, a low plasma level of GDF15 before coronary artery bypass graft surgery was a strong independent predictor of postoperative atrial fibrillation (POAF)." (PMID 34445593, 2021). "Additionally, GDF-15 levels wereassociated with increased risks of cardiovascular death, acute kidney injury, andspontaneous MI, but not with atrial fibrillation." (PMID 40351689, 2025). "In another study of 1941 patients, comparing NT-proBNP and GDF-15 levels in patients with atrial fibrillation versus sinus rhythm, GDF-15 levels were not significantly influenced by the presence of atrial fibrillation, after adjustment for clinical confounders." (PMID 39200768, 2024).
COVID-19 (52 papers, 2020 to 2025). A disease caused by infection with severe acute respiratory syndrome coronavirus 2. "A Norwegian study showed that higher concentrations of GDF-15 were associated with SARS-CoV-2 viremia, hypoxemia, and worse outcomes." (PMID 35464749, 2022). "GDF-15 is a pleiotropic molecule involved in the pathophysiology of cancers, cardiac disease, COVID-19, hyperemesis gravidarium and is tightly linked to stress pathways." (PMID 39989973, 2025). "Elevated levels of serum GDF-15 in the acute phase of COVID-19 were associated with the presence of symptoms, including fatigue, decline in focus, and pain, in non-hospitalized patients three months after infection in the present study." (PMID 38826986, 2024). "In COVID-19 setting, higher GDF-15 plasma levels have been associated with lower SpO2/FiO2 ratio, and therefore with pulmonary dysfunction." (PMID 38700782, 2024). "Dynamic changes in the GDF15 level are furthermore closely associated with COVID-19 progression, and they are used as a useful marker for identifying patients with poor respiratory function." (PMID 37093513, 2024). "In this cohort of hospitalized COVID-19 patients, novel inflammatory biomarkers, including GDF-15, suPAR and PIVKA II were associated with some patient’s clinical characteristics, complications, and poor outcomes." (PMID 38700782, 2024). "Elevated levels of GDF15 and NT-proBNP in individuals diagnosed with COVID-19 have been linked to more severe outcomes." (PMID 39256775, 2024). "In basic logistic regression models, GDF15 was associated with subsequent hospitalisation due to COVID-19 (odds ratio (OR) per SD = 2.0, 95% confidence interval (CI) = [1.2, 3.4], FDR P = 0.037), as opposed to having COVID-19 without hospitalisation." (PMID 39256775, 2024). "Plasma ACBP concentrations were associated with age (r=0.29, p<0.001), with levels of GDF-15, a biomarker of aging (r=0.29, p<0.0001), as well as with ferritin levels, which is an established marker of COVID-19 severity (r=0.3, p<0.001)." (PMID 39835130, 2024). "Our findings support previous work identifying associations between GDF15 and Nt-proBNP protein levels and severe COVID-19 outcomes in hospitalised individuals." (PMID 39256775, 2024). "Increased growth differentiation factor 15 (GDF-15) levels were positively associated with COVID-19 severity in a relatively large proteomic study in Canada." (PMID 38791465, 2024). "The IVW method showed that GDF-15 increased the risk of severe COVID-19 in COVID patients (OR = 1.10, 95% CI 1.03–1.19; P = .006)." (PMID 37773870, 2023). "Sensitivity analysis of the causal relationship between GDF-15 and susceptibility, hospitalization, and severe cases of COVID-19." (PMID 37773870, 2023). "Another study observed increased levels of GDF-15 in patients with fatal outcomes of COVID-19, and the association remained significant even after adjusting for sepsis-related organ failure assessment." (PMID 37568870, 2023). "Strengths of our study include being the first to use Mendelian randomization analysis to reveal the association between GDF-15 (a biomarker for metformin) and COVID-19 from a genetic perspective." (PMID 37773870, 2023). "When measured in hospitalized COVID-19 patients GDF15 is independently associated with ICU admission or death." (PMID 37582864, 2023). "The first set was GDF-15 genome-wide association study (GWAS) data from a study with 5440 participants, while the second set was COVID-19 GWAS data from the Host Genetics Initiative (HGI) GWAS meta-analysis." (PMID 37773870, 2023). "Smaller studies have also reported associations between GDF-15 and COVID-19 severity, with dynamic changes in GDF-15 closely linked to disease progression." (PMID 37568870, 2023). "The underlying mechanism for increasing GDF15 serum level in COVID-19 patients with GIT injury and/or acute hepatic damage is due to hyperinflammation, oxidative stress and exaggeration of inflammatory signaling pathways." (PMID 36140453, 2022).
COVID-19 (continued). "Altogether, high levels of GDF-15, a stress-related cytokine, have been associated with the progression and severity of various conditions including COVID-19." (PMID 35251002, 2022). "The present study adds information indicating that GDF-15 was associated with late recovery or death and was an important biomarker to predict late recovery or death only in COVID-19 patients treated in the ICU." (PMID 35095877, 2021). "Remarkably, in the current study, we found GDF15 levels to be closely associated with disease progression of COVID-19." (PMID 34335566, 2021). "In conclusion, our data support GDF-15 as a biomarker associated with pulmonary impairment in COVID-19 and so can potentially be useful in stratifying COVID-19 cases by severity." (PMID 34829345, 2021). "New data in COVID-19 patients has shown that GDF15 presents a strong association with levels of soluble angiotensin-converting enzyme 2 (sACE2)." (PMID 34445593, 2021). "The increased GDF-15 concentrations seen in patients with moderate and severe disease supports the findings of a recent study where higher GDF-15 levels were associated with viremia, hypoxemia, or worse clinical outcomes in patients hospitalized with COVID-19." (PMID 34333238, 2021). "Other recently-published results indicate that circulating GDF15 levels are elevated in patients hospitalized with COVID-19, and higher concentrations are associated with SARS-CoV-2 viremia, hypoxemia, and worse outcomes." (PMID 34445593, 2021). "GDF15 levels were observed to be associated with the severity of COVID-19 and the dynamic change of GDF15 levels was closely associated with the COVID-19 disease progression." (PMID 34335566, 2021). "Another study has reported that Growth Differentiation Factor 15 (GDF-15) is increased in patients who are hospitalized with COVID-19 and higher levels are associated with a worse outcome." (PMID 34943875, 2021). "Our data support the value of GDF-15 as a biomarker associated with pulmonary impairment in COVID-19." (PMID 34829345, 2021). "The AUC value of 0.89 indicated the serum GDF15 level to be an efficient diagnostic indicator of disease severity in COVID-19 patients." (PMID 34335566, 2021). "GDF-15 and IL-6 appeared to be related with disease severity of COVID-19, but their levels were higher in sepsis than in COVID-19 and were associated with prognosis in sepsis." (PMID 35095877, 2021). "Accordingly, we have previously demonstrated that GDF-15 is linked to COVID-19 severity as well." (PMID 39835130, 2024). "In conclusion, this study reaffirms the significance of commonly used laboratory parameters and clinical scores in the evaluation of COVID-19, but it also introduces the potential for a new diagnostic approach and research concerning GDF-15 levels in this widespread disease." (PMID 38672113, 2024). "GDF-15 is associated with the severity and prognosis of acute COVID-19." (PMID 38826986, 2024). "Several reports show the association between the levels of GDF-15 and disease severity in COVID-19." (PMID 36331721, 2023). "Causal effects of GDF-15 on common risk factors for COVID-19." (PMID 37773870, 2023). "This shows that GDF-15 may be able to detect silent hypoxemic patients, a COVID-19 sign that has been linked to significantly higher risk." (PMID 37974205, 2023). "Our study supports the notion that GDF-15 increases the risk of severe COVID-19 in patients." (PMID 37773870, 2023). "The authors also reported a correlation between GDF-15 and detectable SARS-CoV-2 viremia as well as hypoxemia in their study population." (PMID 35326373, 2022). "The iron overload associated with overexpression of GDF-15 in inflammatory states could lead to increase ferritin, another crucial biomarker in stratifying disease severity in COVID-19." (PMID 35251002, 2022). "Studies reporting an association between GDF-15 and COVID-19 severity." (PMID 35251002, 2022).
COVID-19 (continued). "Altogether, this could partly explain the relationship between the elevated plasma GDF-15 levels, underlying anemia, and severity of COVID-19 in chronic inflammatory conditions especially ESKD." (PMID 35251002, 2022). "In conclusion, GDF15 is an anti-inflammatory cytokine that could be associated with the COVID-19 severity." (PMID 36140453, 2022). "High circulating levels of GDF-15 have been associated with chronic inflammatory conditions including renal, lung, liver and cardiovascular diseases, rheumatoid arthritis, cancers, anemia and infections such as COVID-19." (PMID 35251002, 2022). "GDF15 is an anti-inflammatory cytokine and increased GDF15 could be a compensatory mechanism against hyperinflammation and exaggerated immune response in COVID-19 so that it acts as a pathogenic marker." (PMID 36140453, 2022). "Furthermore, the association between GDF-15 and COVID-19 in CKD patients has been poorly investigated." (PMID 36552007, 2022). "In addition to these cytokines, elevated serum GDF-15, which we found to be increased by COVID-19 plasma exosomes, was associated with most hospitalized COVID-19 patients and SARS-CoV-2 viremia, hypoxemia, and worse outcome." (PMID 36526691, 2022). "The elevated serum levels of GDF-15 in COVID-19 patients with ARDS indicated that GDF-15 may be associated with ARDS caused by a virus infection." (PMID 35784345, 2022). "Thus, the objective of the present critical review was to find the critical association between GDF15 and COVID-19 regarding the disease severity and clinical outcomes." (PMID 36140453, 2022). "Finally, correlations between I-FABP with other biomarkers of COVID-19 prognosis should be informative, for instance, with Growth differentiation factor 15 (GDF-15) is associated with severe COVID-19, hypoxemia, and SarsCov2 viremia." (PMID 33857216, 2021). "We hypothesized that circulating GDF-15 would be associated with COVID-19 disease severity." (PMID 38686386, 2024). "Despite the limitations, our study provides convincing evidence that in patients with COVID-19, the levels of GDF15 and ACE2 could be associated with increased inflammation and disease severity while ACE2 missense SNPs might be linked to infection susceptibility." (PMID 35937703, 2022). "Therefore, GDF15 serum level could be a possible diagnostic and prognostic biomarker in severely affected COVID-19 patients." (PMID 36140453, 2022). "Thus, this critical review aimed to determine the critical association between GDF15 and COVID-19." (PMID 36140453, 2022). "Notably, present data suggests that the predictability of mortality risk in COVID-19 patients by GDF-15 could be stronger in the presence of eGFR < 45 mL/min/1.73 m2." (PMID 36552007, 2022). "However, many studies implicated the role of GDF15 in the pathogenesis and severity of COVID-19." (PMID 36140453, 2022). "Therefore, GDF15 is regarded as a diagnostic and prognostic biomarker in COVID-19 patients." (PMID 36140453, 2022). "In our study, some markers of the intussusceptive vascular remodeling typical for COVID-19 were upregulated during the acute (Ccl12, Gdf15, and Cd163) or chronic phase (Col3a1, Cxcl12)." (PMID 40021627, 2025). "Severe COVID-19 groups also had significantly greater plasma GDF-15 elevation compared to moderate and mild COVID-19 groups (p=0.0049, p<0.0001 respectively)." (PMID 38686386, 2024). "In all COVID-19 infected patients, GDF-15 levels were consistently higher in those with comorbidities groups." (PMID 38686386, 2024). "This prospective observational cohort pilot study, conducted at the University Hospital Centre Osijek, aimed to investigate the prognostic significance of GDF-15 in COVID-19 patients in relation to mortality, ICU admission, and length of hospitalization." (PMID 38672113, 2024). "Our results indicate that plasma GDF-15 levels would be a better predictor of COVID-19 severity in hospitalized patients than other commonly used markers." (PMID 38686386, 2024).
COVID-19 (continued). "We aimed to confirm and expand previous research findings and validate the prognostic value of GDF-15 as a marker for COVID-19 severity in a large, more diverse population with a range of comorbidities, in hospitalized patients before the vaccination era." (PMID 38686386, 2024). "Given that SARS-CoV-2 is known for both direct and indirect endothelial damage, an elevation of GDF-15 in COVID-19 can be anticipated." (PMID 38672113, 2024). "In COVID-19 patients, the GDF-15 serum levels resulted higher according to the presence of two or more comorbidities (p = 0.021)." (PMID 38700782, 2024). "We showed consistent elevation of plasma GDF-15 in severe COVID-19 patients compared to those with mild and moderate." (PMID 38686386, 2024). "ROC analysis was conducted to evaluate the predictive ability of plasma GDF-15 to discriminate mild and severe COVID-19 states (including fatal cases)." (PMID 38686386, 2024). "Reduced FVC and FEV1 have been previously associated with higher GDF-15 levels, specifically in some diseases such as COPD or COVID-19." (PMID 39644331, 2024). "This prospective observational study aimed to investigate the prognostic roles of GDF-15 and routine clinical laboratory parameters in COVID-19 patients." (PMID 38672113, 2024). "In the present study, COVID-19 patients showed an increased inflammatory status, as documented in particular by the high serum levels of GDF-15, PIVKA-II, as well as CRP." (PMID 38700782, 2024). "Consistently, we found increased plasma GDF-15 levels in COVID-19 patients with different pathologies, which contributed to the association between GDF-15 levels and increased severity and mortality rate." (PMID 38686386, 2024). "We next examined the impact of these comorbidities on GDF-15 expression in severe and fatal COVID-19 patients." (PMID 38686386, 2024). "Plasma GDF-15 levels were significantly higher by 1.7-fold in COVID-19 infected participants compared to controls (p<0.0001)." (PMID 38686386, 2024). "Plasma levels of GDF-15 were notably higher during the first wave compared to those observed during the second COVID-19 wave (p<0.001)." (PMID 38686386, 2024). "Future studies should focus on evaluating the potential impact of COVID-19 vaccination on the prognostic value of GDF-15 in disease severity in vaccinated COVID-19 population and in recovered person who get reinfected." (PMID 38686386, 2024). "This study evaluated the predictive and diagnostic value of routine laboratory parameters, clinical scores (CURB-65 and qSOFA scores), and GDF-15 in hospitalized COVID-19 patients." (PMID 38672113, 2024). "In this large cohort of patients assessed before COVID-19 vaccination, using proteomics, we found higher plasma levels of GDF-15 in persons with COVID-19 compared to hospitalized controls." (PMID 38686386, 2024). "Since there is a receptor for GDF-15 in the brainstem, it would be interesting to observe its levels in patients with COVID-19 and neurological comorbidity." (PMID 38672113, 2024). "Proteomics showed that plasma GDF-15 levels were higher in COVID-19 patients compared to hospitalized controls." (PMID 38686386, 2024). "This study aimed to assess the levels of GDF-15 in children with COVID-19 as a biomarker of myocardial and muscular affection in those patients." (PMID 37974205, 2023). "Using multivariate linear regression analysis, higher GDF-15 was associated with lower ejection fraction and higher INR in COVID-19 children." (PMID 37974205, 2023). "A study conducted in Norway in hospitalized COVID-19 patients found significantly higher levels of GDF-15 levels in those who required ICU admission or experienced death during hospitalization." (PMID 37568870, 2023). "Based on these findings, GDF-15, which is easily available by commercial assays on large automated analytic platforms, may represent a clinically useful risk stratification tool that provides important pathophysiological insights in patients hospitalized with COVID-19." (PMID 37974205, 2023).